PDPR (pyruvate dehydrogenase phosphatase regulatory subunit)
Description:
Decreases the sensitivity of PDP1 to magnesium ions, and this inhibition is reversed by the polyamine spermine.
Synonyms: PDP3
Tractability: PROTAC: ubiquitination databases record sites on it; its protein half-life has been measured.
Gene: Protein-coding gene on chromosome 16 (70,114,246 to 70,162,537, forward strand). Ensembl gene ENSG00000090857.
Subcellular location: Mitochondrion matrix
Subcellular location (Human Protein Atlas): Mitochondria
Pathways (Reactome):
Metabolism: Regulation of pyruvate dehydrogenase (PDH) complex
Gene Ontology:
Biological process: positive regulation of pyruvate decarboxylation to acetyl-CoA
Cellular component: mitochondrion; cytoplasm; mitochondrial matrix; pyruvate dehydrogenase (lipoamide) phosphatase complex
Genetic constraint (gnomAD): Loss-of-function variants: 46 observed, 71.22 expected, observed/expected ratio (o/e) 0.65, 90% interval 0.51 to 0.83. The upper end of that interval is the gene's LOEUF score, 0.83, which puts it in group 3 of 6, group 1 being the genes least tolerant of losing a copy. Missense variants: 599 observed, 809.26 expected, observed/expected ratio (o/e) 0.74, 90% interval 0.69 to 0.79. Synonymous variants: 249 observed, 282.3 expected, observed/expected ratio (o/e) 0.88, 90% interval 0.8 to 0.98.
Homologues: Orthologues: macaque PDPR (99% identical), dog PDPR (95% identical), rabbit PDPR (95% identical), pig PDPR (93% identical), mouse Pdpr (92% identical), rat Pdpr (92% identical), guinea pig PDPR (89% identical), tropical clawed frog pdpr (78% identical), zebrafish pdpr (72% identical), Caenorhabditis elegans M04B2.4 (8% identical), Drosophila melanogaster CG3270 (8% identical), Drosophila melanogaster l(2)37Bb (8% identical). Paralogues in human: SARDH (32% identical), DMGDH (31% identical), AMT (11% identical), L2HGDH (10% identical), FOXRED1 (9% identical), YPEL3 (3% identical), YPEL2 (3% identical), YPEL1 (3% identical), YPEL4 (3% identical), YPEL5 (3% identical).
Diseases named in the same sentence as PDPR in open-access papers:
PDPR is named in the same sentence as 12 diseases in open-access papers, as found by Europe PMC text mining. Sharing a sentence is not in itself a finding about the gene and the disease. The quoted sentences say what the papers report.
amyloidosis (1 paper, 2021). A disorder characterized by the localized or diffuse accumulation of amyloid protein in various anatomic sites. "The MMSE‐correlated DEPs were mainly involved in amyloidosis (DNM1, UBR1, OPTN, FERMT2), CNS disorder (WIPF1) and energy metabolism (COA6, COX7C, PDPR) processes." (PMID 34528736, 2021).
Azoospermia (1 paper, 2022). Absence of any measurable level of sperm,whereby spermatozoa cannot be observed even after centrifugation of the semen pellet. "In non-obstructive azoospermia, we show that the genes pyruvate dehydrogenase phosphatase regulatory (PDPR) and sorbitol dehydrogenase regulatory (SORD) were decreased (downregulated)." (PMID 36293429, 2022).
behavior disorder (1 paper, 2021). "Here, we propose that the de novo PDPR stop-gain variant might contribute to the language delay and behavior disorder observed in patient IV." (PMID 34948243, 2021).
bipolar disorder (1 paper, 2015). A disorder of the brain that causes unusual shifts in mood, energy, activity levels and the ability to carry out day-to-day tasks. "We identified three rare deletions in KCNJ6, UNC13C, OTOL1 and 7 rare duplications in CNTNAP2/MIR548F3, CORO7/VASN, DTNB, EMID2, KCNF1, PDPR and SGTA/THOP1 that are present in children with bipolar disorder (and their parents)." (PMID 25887117, 2015).
depression (1 paper, 2025). "An integrated analysis identified 434 preeclampsia-associated secretory protein genes and 1165 depression-related pathogenic genes, from which three signature biomarkers, CLEC3B, CTLA4, and PDPR, were ultimately determined via LASSO regression and random forest algorithms." (PMID 41409330, 2025).
cancer (3 papers, 2017 to 2021). A tumor composed of atypical neoplastic, often pleomorphic cells that invade other tissues. "PDK1, PDK2, PDK3, PDK4, PDP2, and PDPR genes can regulate the glucose metabolism and glycolysis of cancer cells." (PMID 34199666, 2021). "The primary cultured cells obtained from the malignant tumors developed by transplanting miPSCs treated with PD0325901, CHIR99021 and Dasatinib were named as miPS-LLCcm-PDpr, miPS-LLCcm-CHpr, miPS-LLCcm-Dapr, respectively." (PMID 32572057, 2020).
tumor (2 papers, 2021). "Tumor tissues with high c-Met expression level in TCGA have increased expression of H6PD, PDK2, PDK4, PDPR, PKLR, SLC2A2 genes whereas decreased expression of GYS1, HK1, HK2, SLC2A1, significantly." (PMID 34059694, 2021).
neurodevelopmental disorder (1 paper, 2023). A behavioral and cognitive disorder with onset during the developmental period that involves impaired or aberrant development of intellectual, motor, or social functions. "To date, PDPR, LRRC18, and PARP14 have not been associated with neurodevelopmental disorders." (PMID 38025430, 2023).
PDPR also shares sentences with these, for which no sentence is quoted: heart attack (2 papers); infection (2); coronary artery disease (1); preeclampsia (1).